ZDHHC4 (zDHHC palmitoyltransferase 4)
Description:
Palmitoyltransferase that catalyzes the addition of palmitate onto protein substrates including the D(2) dopamine receptor DRD2, GSK3B or MAVS. Mediates GSK3B palmitoylation to prevent its AKT1-mediated phosphorylation leading to activation of the STAT3 signaling pathway. Also catalyzes MAVS palmitoylation which promotes its stabilization and activation by inhibiting 'Lys-48'- but facilitating 'Lys-63'-linked ubiquitination.
Synonyms: ZNF374; FLJ10479
Tractability: Antibody: UniProt places it where antibodies can reach, with high confidence; UniProt predicts a signal peptide or a membrane-spanning region; its Gene Ontology location is reachable by antibodies, with medium confidence.
Gene: Protein-coding gene on chromosome 7 (6,577,405 to 6,589,374, forward strand). Ensembl gene ENSG00000136247.
Subcellular location: Endoplasmic reticulum membrane; Golgi apparatus membrane; Cell membrane
Gene Ontology:
Molecular function: palmitoyltransferase activity; protein binding; protein-cysteine S-palmitoyltransferase activity
Biological process: positive regulation of innate immune response; protein localization to plasma membrane; protein targeting to membrane
Cellular component: endoplasmic reticulum; endoplasmic reticulum membrane; Golgi apparatus; Golgi membrane; plasma membrane
Genetic constraint (gnomAD): Loss-of-function variants: 40 observed, 34.64 expected, observed/expected ratio (o/e) 1.15, 90% interval 0.9 to 1.5. The upper end of that interval is the gene's LOEUF score, 1.5, which puts it in group 6 of 6, group 1 being the genes least tolerant of losing a copy. Missense variants: 439 observed, 416.38 expected, observed/expected ratio (o/e) 1.05, 90% interval 0.97 to 1.14. Synonymous variants: 184 observed, 168.49 expected, observed/expected ratio (o/e) 1.09, 90% interval 0.97 to 1.23.
Homologues: Orthologues: macaque ZDHHC4 (94% identical), chimpanzee ZDHHC4 (94% identical), pig ZDHHC4 (78% identical), dog ZDHHC4 (77% identical), mouse Zdhhc4 (74% identical), guinea pig ZDHHC4 (72% identical), rat Zdhhc4 (71% identical), rabbit ZDHHC4 (54% identical), zebrafish zdhhc4 (44% identical), tropical clawed frog zdhhc4 (44% identical), Caenorhabditis elegans dhhc-4 (14% identical), Caenorhabditis elegans dhhc-2 (14% identical), and 7 more. Paralogues in human: ZDHHC23 (22% identical), ZDHHC1 (19% identical), ZDHHC14 (18% identical), ZDHHC9 (17% identical), ZDHHC18 (17% identical), ZDHHC11 (17% identical), ZDHHC15 (17% identical), ZDHHC11B (17% identical), ZDHHC19 (16% identical), ZDHHC20 (16% identical), ZDHHC7 (16% identical), ZDHHC6 (15% identical), and 5 more.
Diseases named in the same sentence as ZDHHC4 in open-access papers:
ZDHHC4 is named in the same sentence as 51 diseases in open-access papers, as found by Europe PMC text mining. Sharing a sentence is not in itself a finding about the gene and the disease. The quoted sentences say what the papers report.
breast carcinoma (6 papers, 2013 to 2026). "In contrast, P104S mutation (breast cancer) within the third transmembrane segment of zDHHC4 substantially diminished auto-S-palmitoylation, as did L215S mutation (testicular germ cell tumor) in the third transmembrane segment of zDHHC14." (PMID 39800157, 2025). "Therefore, loss of zDHHC4 activity would promote pathological angiogenesis and accelerate breast cancer progression." (PMID 39800157, 2025). "Certain circRNAs identified in our analysis demonstrated exceptionally strong discriminatory power across breast cancer subtypes, e.g., hsa_circRNA_104310 (host gene: ZDHHC4), hsa_circRNA_404935 (ZBTB16), hsa_circRNA_003641 (ATM), and hsa_circRNA_102445 (CARM1)." (PMID 41516402, 2026). "Several circRNAs identified in our analysis, including hsa_circRNA_104310 (ZDHHC4, AUC = 0.80), hsa_circRNA_404935 (ZBTB16, AUC = 0.882), hsa_circRNA_003641 (ATM, AUC = 0.876), and hsa_circRNA_102445 (CARM1, AUC = 0.812), demonstrated strong discriminatory power across breast cancer subtypes." (PMID 41516402, 2026).
glioblastoma (6 papers, 2022 to 2025). The most malignant astrocytic tumor (WHO grade IV). "One recent study found that GSK3β palmitoylation, mediated by ZDHHC4, decreases p-Ser9 and increases p-Tyr216, leading to continuous activation of GSK3β, promoting tumorigenicity of glioblastoma stem cells." (PMID 40814339, 2025). "ZDHHC4 mediates the palmitoylation and activation of GSK3β, sustaining the stemness of temozolomide-resistant glioblastoma multiforme (GBM) by activating the EZH2-STAT3 signaling axis." (PMID 40814339, 2025). "In glioblastoma (GBM) stem cells, palmitoylation Glycogen synthase kinase 3β (GSK3β) at Cys14 mediated by ZDHHC4 can activate STAT3 signaling to improve the stemness of temozolomide (TMZ)-resistant GBM." (PMID 39877903, 2025).
melanoma (5 papers, 2018 to 2026). A malignant, usually aggressive tumor composed of atypical, neoplastic melanocytes. "Currently, ZDHHC4 has been shown to functionally affect the palmitoylation of MAVS in murine B16 melanoma cells." (PMID 39621307, 2024). "Notably, ZDHHC4 has been demonstrated to enhance MAVS-mediated immune responses in murine B16 melanoma cells." (PMID 39621307, 2024). "Thus, our collaborative research with W. Sheng’s team has shed light on the functional roles of ZDHHC12 in human and murine macrophages and ZDHHC4 in murine B16 melanoma cells, revealing their ability to promote MAVS-mediated immune responses." (PMID 39621307, 2024). "Currently, ZDHHC4 has been shown to functionally affect the palmitoylation and activation of MAVS in the murine B16 melanoma cell line." (PMID 39621307, 2024).
diabetic cardiomyopathy (3 papers, 2024 to 2025). Diabetic cardiomyopathy is a disorder of the heart muscle in people with diabetes. "Knockdown of ZDHHC4 in cardiomyocytes reversed the increase in CD36 palmitoylation induced by TGR5 deletion, suggesting that the TGR5-ZDHHC4 pathway is a key target for intervening in lipid metabolism in diabetic cardiomyopathy." (PMID 40959086, 2025). "In diabetic cardiomyopathy, activation of Takeda G-protein-coupled receptor 5 (TGR5), a bile acid receptor, triggers cyclic AMP-protein kinase A (cAMP-PKA)-mediated phosphorylation and consequent inactivation of ZDHHC4." (PMID 41306774, 2025).
diabetes (1 paper, 2025). "Activation of the FoxO1 transcription factor in diabetes upregulates the transcription of the S-acylating enzyme zDHHC4, driving increased CD36 S-acylation and membrane relocalization." (PMID 40357580, 2025). "Using a combination of in silico analyses, genetic cellular studies, pharmacological approaches, and cardiomyocyte-specific knockout mice, we demonstrate that the upregulation of zDHHC4 in diabetes is mediated by activation of the FoxO1 transcription factor." (PMID 40357580, 2025). "Induction of diabetes in αMHCCre control mice increased zDHHC4 expression by 78% and increased CD36 S-acylation 1.8-fold." (PMID 40357580, 2025). "To identify the transcription factor responsible for increased zDHHC4 expression in diabetes, we examined its promotor region using the JASPAR Transcription Factor Track Settings, an open-access database of transcription factors binding profiles, visualized on the UCSC browser." (PMID 40357580, 2025). "Inducing diabetes in the FoxO1-deficient littermates (Foxo1Cardiac−/−) prevented this response, with no significant increase in zDHHC4 expression or CD36 S-acylation relative to controls in response to diabetes." (PMID 40357580, 2025).
glioma (1 paper, 2022). A benign or malignant brain and spinal cord tumor that arises from glial cells (astrocytes, oligodendrocytes, ependymal cells). "In terms of glioma patient prognosis, higher levels of ZDHHC4 represented shorter overall survival and disease-free survival, which were obtained from TCGA, Chinese Glioma Genome Atlas (CGGA), and REMBRANDT." (PMID 35606353, 2022). "Compared with normal brain tissue, the expression level of ZDHHC4 was higher in low-grade glioma (LGG) and GBM, especially GBM." (PMID 35606353, 2022). "Immunohistochemical staining results of 125 brain tissue samples showed that the expression trends of ZDHHC4, p-GSK3β (Y216), and p-STAT3 (Y705) were consistent and positively correlated with the pathological grade of glioma." (PMID 35606353, 2022).
Obesity (1 paper, 2025). Accumulation of substantial excess body fat. "In obesity and T2DM, CD36 becomes constitutively localized at the membrane through S-acylation by zinc finger DHHC-type palmitoyltransferase 4 (zDHHC4), which is upregulated by forkhead box protein O1 (FoxO1) signaling." (PMID 41002965, 2025).
Parkinson disease (1 paper, 2022). A progressive degenerative disorder of the central nervous system characterized by loss of dopamine producing neurons in the substantia nigra and the presence of Lewy bodies in the substantia nigra and locus coeruleus. "In contrast, the projected-palmitoylome of DG granule cells which have the highest expression of Zdhhc21, Zdhhc4, Zdhhc24, and Zdhhc8 generated KEGG pathways related to ‘Ribosome’, ‘Cholinergic synapse’, and ‘Parkinson’s disease’." (PMID 35819139, 2022).
tumor (42 papers, 2010 to 2026). "In the extreme limiting dilution assay (ELDA), the depletion of ZDHHC4 obviously inhibited the formation of tumor spheres in SF126R cells as evidenced by the decrease in the number, size, and frequency of stem cells." (PMID 35606353, 2022). "Clinically, the expression level of ZDHHC4 was upregulated in GBM, which significantly correlated with tumor grade and poor prognosis." (PMID 35606353, 2022). "In this study, we demonstrated that ZDHHC4/12/18/24 and APT2 may affect CD276 palmitoylation and, therefore, tumor growth." (PMID 38177255, 2024). "TMZ treatment alone did not reduce the volume of the tumor, and knockdown of ZDHHC4 effectively restored the sensitivity of the tumor tissue to TMZ." (PMID 35606353, 2022).
cancer (13 papers, 2015 to 2025). A tumor composed of atypical neoplastic, often pleomorphic cells that invade other tissues. "One example is represented by our finding that a cancer-related mutation of zDHHC4 distant from the active site (Pro104) greatly suppressed zDHHC activation." (PMID 39800157, 2025).
ZDHHC4 also shares sentences with these, for which no sentence is quoted: infection (4 papers); Autoimmunity (3); COVID-19 (3); lung carcinoma (3); colorectal cancer (2); fungal infection (2); hepatocellular carcinoma (2); multiple sclerosis (2); Airway obstruction (1); Allergy (1); anorexia nervosa (1); asthma (1); breast tumors (1); cardiovascular diseases (1); cervical cancer (1); cervical squamous intraepithelial lesions (1); Coccidioides infection (1); colitis (1); cryptococcal infections (1); experimental autoimmune encephalomyelitis (1); gastric cancer (1); intestinal infections (1); intraepithelial neoplasia (1); leukaemia (1); lung adenocarcinoma (1); lymph node metastasis (1); malaria (1); neoplastic disorder (1); osteosarcoma (1); ovarian carcinoma (1).
A further 11 diseases each share a sentence with ZDHHC4 in 1 paper.